STAT6 (signal transducer and activator of transcription 6)
Diseases named in the same sentence as STAT6 in open-access papers (continued):
Sharing a sentence is not in itself a finding about the gene and the disease.
tumor (continued). "This demonstrated an EV-mediated interaction of tumour promotive effects through promotion of M2 macrophage differentiation, mediated by EV-transferred miR-20a-3p via the SOCS1/STAT6 signalling pathways." (PMID 32054041, 2020). "Platinum-based chemotherapy can interfere with the STAT6-mediated immunosuppression in the TME via downregulation of the expression of PD-L2 on human DCs and tumor cells and increasing tumor T cell recognition." (PMID 33123161, 2020). "Active STAT6 signaling seems to promote Thelper 2 cytokine profiles in CRC and to confer a pro-metastatic and anti-apoptotic tumor phenotype." (PMID 33014816, 2020). "Compared to non-tumor tissue, GBM tissue exhibited a significantly lower percentage of positive staining for STAT6." (PMID 31530290, 2019). "While STAT2 and STAT4 promote the anti-tumor immune response, STAT3 and STAT6 mediate immunosuppression in the TME, and STAT1 and STAT5 have been implicated in both activation and suppression of the anti-tumor immune response." (PMID 31057536, 2019). "During the 9-month observation, the suppression of tumor progression in the STAT6−/− mice became increasingly obvious, and the survival rate is higher in the STAT6−/− mice than in WT mice, 94.44 vs. 83.33%, respectively." (PMID 31798581, 2019). "Immunohistochemical staining showed a Ki67 index of 8% in the tumour cells, strong and diffuse positivity for CD34 and STAT6, and zonal positivity for vimentin and CD99." (PMID 31228959, 2019). "However, the molecular mechanism of STAT6 regulation by tumor viruses is still unknown." (PMID 30532138, 2018). "Regarding IL-35-activated signals in metastatic tumor cells, GATA3 activated by STAT6 is the main pathway induced by IL-35." (PMID 30218063, 2018). "Tumor cells were pretreated with cisplatin for different time periods, washed and subsequently pulsed with cytokines after which STAT1, STAT3 or STAT6 phosphorylation was assessed." (PMID 28903353, 2017). "Immunohistochemistry showed that IR-induced IL-4 increased the expression of major components related to p-Stat6, mesenchymal trait marker, Vimentin; invasiveness marker, MMP-9; stemness maintenance marker, Sox2; and tumor proliferation marker, Ki-67." (PMID 27895317, 2016). "In summary, IR affects the miR-340/429/IL-4/β-catenin/Stat6 signaling axis through activation of JAK and JNK, effectively enhancing tumor progression and metastasis of human carcinomas." (PMID 27895317, 2016). "In addition, tumor cell‐expressed HVEM altered chemokine expression (CXCL1/9/10/11 and CCL2/4/5) and STAT signal activation (STAT5 and STAT6) in ID8 cells." (PMID 40105652, 2025). "Tumor cells are positive for androgen receptors, actin, smooth muscle, and β-catenin protein, while negative for STAT6 stains." (PMID 41226013, 2025). "Activation of STAT6 may influence the inflammatory environment and tumor development in HT patients, and in PTC patients, it may promote tumor progression and metastasis by affecting immune cell polarization and angiogenesis." (PMID 40230479, 2025). "The blood vessels have a hemangiopericytomatous structure, and tumor cells express STAT6 but not SMA, estrogen receptor, or progesterone receptor." (PMID 41137250, 2025). "Beyond targeting STAT3 and STAT6, other TAM reprogramming strategies include stimulating M1 polarisation using agents like IFN-gamma, blocking immunosuppressive signals such as PD-L1, or enhancing phagocytosis of tumour cells." (PMID 41155941, 2025). "We identified 6284 NAB2 peaks, 1640 STAT6 peaks, and 38,036 RNAPII peaks in primary tumor cells." (PMID 40875449, 2025). "While many studies have reported that miRNAs can directly target TRIM24 and regulate its roles in cell proliferation, tumor formation, and inflammation, this is the first identification of the macrophage polarization regulation pathways miR‐137‐3p/TRIM24/STAT6." (PMID 41395781, 2025).
tumor (continued). "According to the results of in vitro experiments, GAN could inhibit tumor growth, suppress the tissue infiltration of CD206 cells, and inhibit the phosphorylated expression of STAT6." (PMID 38244580, 2024). "Although the tumor samples showed positive STAT6 expression, EMA and CD34 were found to be negative, and the proliferation index based on Ki67 was low." (PMID 38341593, 2024). "Nuclear STAT6 expression and specific NAB2-STAT6 fusion aid in tumor confirmation." (PMID 38982409, 2024). "In this study, we have shown that STAT6 3′ UTR-targeting ASO 993523 effectively decreased the expression of NAB2-STAT6 fusion transcripts both in vitro and in vivo and, importantly, exerted anti-tumor impact in the SFT PDX model." (PMID 38511173, 2024). "In our experience, two tumor diagnoses were revised based on the NGS finding of NAB2::STAT6 fusion (patient #32) and absence of MN1 alteration (patient #30)." (PMID 38440233, 2024). "In contrast to its anti-tumor immunity in melanoma, TGR5 is required for the M2 polarization of TAMs, and TGR5 suppresses anti-tumor immunity in NSCLC through the TAM-mediated CD8+ T-cell suppression and the activation of the cAMP-STAT3/STAT6 signaling, implying its onco-immunological role in NSCLC." (PMID 38203175, 2023). "In conclusion, we discovered a previously unknown pro‐tumorous mechanism in which the CYP2E1‐PPAR‐γ‐STAT‐1/NF‐κB/STAT‐3/STAT‐6 axis induced GBM cell proliferation and inhibited apoptosis to fuel tumorigenesis and tumor growth." (PMID 37283464, 2023). "As normalized concentrations of STAT6 are lower than 0.35, regardless of the value of NFкB, the macrophage will shift to an anti-tumor/regulatory hybrid M1M2b." (PMID 37283734, 2023). "Immunohistochemically, the tumor cells were positive for CD34 and STAT6." (PMID 37315497, 2023). "In our case, the tumor presented with strongly positive STAT6 and CD34, moderately positive CD99, negative EMA and S-100 markers, mitoses <5/10 HPF, and absence of necrosis, suggesting the diagnosis of grade 1 SFT." (PMID 36060387, 2022). "Indeed, myeloid-specific deletion of cholesterol efflux genes ABCA1 and ABCG1 or inhibition of IL-4R signaling, STAT6, or PI3K has been found to significantly impair tumor progression in an ovarian cancer model." (PMID 34876704, 2022). "In vivo, the engineered nanoliposomes are distributed specifically to M2-like macrophages and, upon delivery of the STAT6 inhibitor (AS1517499), zoledronic acid or muramyl tripeptide, these cells promote reduction of the premetastatic niche and/or tumor growth." (PMID 35927238, 2022). "In addition, SOCS1 inhibition and STAT6 activation can promote the polarization of M2-subtype macrophages, enhance the invasion and migration ability of OSCC cells, and accelerate tumor growth." (PMID 36359867, 2022). "We successfully validated the presence of MDK and absence of STAT6 proteins in corresponding patient tumor tissues of cluster 4 GBM members, with GBM tissues from cluster 1 member GB-300 serving as positive control for STAT6." (PMID 34502484, 2021). "STAT6 was detected in the primary differentiated tumor but not in the primary dedifferentiated tumor or lung/liver metastases." (PMID 35004271, 2021). "In neoplastic diseases, MDSCs are major contributors to the intra-tumoral arginase activity observed in both preclinical models and cancer patients, in which tumor-derived factors, such as PGE2, can induce Arg1 expression via STAT3 or STAT6." (PMID 34037806, 2021). "Moreover, IL-4, through activation of NFAT and STAT6 transcription factors, induces the expression of IGF-1 in TAMs, which signals neighboring tumor cells to activate the PI3K pathway to promote cell proliferation and tumor expansion." (PMID 34949203, 2021). "Moreover, CD163 expression was positively correlated with most gene markers of these tumor-infiltrating immune cells in both the TCGA and CGGA cohorts, including CD8A, CD8B, STAT6, STAT5A, and PDCD1." (PMID 34395626, 2021).
tumor (continued). "Accordingly, it is plausible that STAT6-dependent regulation of macrophage polarization towards an M2-like phenotype may play an important role in SFT tumorigenesis and tumor progression." (PMID 34299133, 2021). "Various tumor-derived factors have been shown to induce the expansion of myeloid-derived suppressor cells (MDSCs) through multiple pathways, including STAT3 or IL-4Rα-STAT6, resulting in the suppression of T cell function." (PMID 34572829, 2021). "However, at Day 68, the Treg cells frequency dropped in STAT6−/− AOM/DSS animals to similar levels as those in control mice, which is consistent with the fact that there was a lower tumor load." (PMID 33919941, 2021). "Additionally, the tumor load in the WT CAC, WT PC61, and STAT6−/− PC61 mice was similar, demonstrating that STAT6-deficient mice can be made susceptible to CAC development through the early depletion of Treg cells." (PMID 33919941, 2021). "Considering that the inflammation is the main driver of tumor initiation in CAC, one potential mechanism contributing to the suppression of the inflammatory response in STAT6−/− mice may be an increased recruitment of Treg cells." (PMID 33919941, 2021). "In our case, the tumour cells are positive for BCL-2, CD34 and STAT6." (PMID 34849218, 2021). "Immunohistochemical staining is required for the diagnosis of SFTP; the tumor cells are positive for STAT6, CD34, CD99, and BCL2, whereas they are negative for desmin, S-100, and alpha-SMA." (PMID 32638177, 2020). "It is worth mentioning that the IL-4 receptor α-chain-STAT6 pathway does not induce tumor immunosuppression in all tumor microenvironment." (PMID 33330446, 2020). "Cytokines are key components in the tumor microenvironment, and could be involved in the response to chemotherapies in CAC during STAT6-inhibition." (PMID 32244885, 2020). "Various factors in a tumor could induce the expansion or activation of MDSCs through multiple pathways, including STAT3 or IL-4Rα–STAT6 pathways, resulting in the suppression of T-cell function." (PMID 32983146, 2020). "Immunohistochemical analysis of the resected tumor revealed that the tumor cells expressed positive results for CD34, vimentin, and Bcl-2, focally positive for cytokeratin AE1/AE3, and weakly positive for STAT6." (PMID 33188464, 2020). "By immunohistochemistry, the tumor cells stained positively for S-100 (focal +), CD34 (strong +++) and Ki-67 (20%), and negatively for smooth muscle actin, pan-cytokeratin, neurofilament, pan-cytokeratin-L, GFAP, CD31, STAT6, ERG, myogenin, and MyoD1." (PMID 32590748, 2020). "Interestingly, after collecting TAMs from WT and Trim24M−/− tumor-bearing mice through FACS sorting, much more Lys383-acetylated Stat6 was detected by immunofluorescent staining in the nuclei of WT TAMs than those of Trim24-deficient TAMs." (PMID 31554795, 2019). "On day 21, phospho-STAT6 showed differences in tumour-bearing groups when compared to their respective groups without a tumour (phospho-STAT6 was higher in W vs C; P = 0.0287, and was increased in WL compared to L group; P = 0.0087)." (PMID 30975087, 2019). "Regardless, the absence of STAT6 immunostaining in a tumor with morphologic features consistent with SFT/HPC should lead to the consideration of molecular testing to assess for the presence of NAB2–STAT6 fusion." (PMID 30584643, 2019). "Tumor cells were not stained for STAT6, AE1/AE3, Bcl-2, CD34, CD117, Factor VIIIR Ag, or S-100 protein (data not shown)." (PMID 30206803, 2019). "Immunohistologic analysis demonstrated the tumor cells were positive for α-smooth muscle actin, β-catenin and Vimentin, and negative for AE1/AE3, Bcl-2, CD34, CD117, Factor VIIIR Ag, S-100 protein, or STAT6." (PMID 30206803, 2019). "Tumor cells express very little STAT6 or do not express STAT6 at all, suggesting that STAT6 biological activity cannot reside predominantly in the tumor cells." (PMID 31798581, 2019).
tumor (continued). "Mechanically, miR-361 impairs tumor cell proliferation, migration, and invasion by directly targeting and downregulating the expression of FKBP14, MMP-1, SND1, ROCK1, YAP, WT1, RPL22L1 and STAT6." (PMID 31394811, 2019). "A subgroup analysis of p-STAT5 and p-STAT6 protein expression was performed, along with clinicopathological features in the CRC patients, i.e. age, gender, tumor size, tumor site, differentiation degree, infiltration depth, lymphatic metastasis and distant metastasis." (PMID 31718693, 2019). "In the present case, the tumor was sparsely positive for CD34, which was an untypical finding of SFT, but we established the diagnosis of SFT based primarily on diffuse nuclear expression of STAT6." (PMID 31520184, 2019). "Tumor cells were diffusely and strongly positive for β-catenin nuclear staining, but negative for STAT6." (PMID 29168109, 2018). "To further investigate the impact of JAK–STAT6 suppression on metastasis, we orthotopically implanted Stat6-knockdown 4T1 cells in mice and found that the knockdown of Stat6 reduced metastasis without affecting the growth of the primary tumor." (PMID 30218063, 2018). "Exposure to platinum-based drugs can disrupt the STAT6-mediated immunosuppression in the TME by decreasing the expression of PD-L2 on both human DCs and tumor cells, enhancing antigen-specific proliferation and Th1 cytokine secretion, as well as increasing tumor T cell recognition." (PMID 30049987, 2018). "The tumor cells showed strong and diffuse nuclear immunostaining with beta catenin and were negative with STAT6, CD34 and bcl-2." (PMID 29168109, 2018). "It is very interesting that mice lacking STAT6 manifest enhanced tumor immunity to both primary and metastatic mammary carcinomas, and induce spontaneous rejection of implanted tumors." (PMID 28927416, 2017). "In addition it reduces numbers and functions of tumor-infiltrating ISCs by changing the cytokine/chemokine milieu within the TME and inhibiting the activity of the STAT6 signaling pathway within ISCs." (PMID 26943036, 2016). "Significant activation of DNA binding activity of STAT6, phosphorylation of STAT6 as well as IL-4, IL-4Rα and p21 expression were found in the tumor tissues of IL-4 mice compared to non-transgenic mice." (PMID 26993600, 2016). "IHC revealed that the tumor diffusely expressed CD34, CD99, Bcl2, PAX8, NAB2, STAT6, and GRIA2." (PMID 26337721, 2015). "However recent investigations into the genetics of the tumor has revealed the overexpression of STAT6 protein, a result of gene-fusion on chromosome 12q13 which leads to a NAB2-STAT6 fusion product." (PMID 26322223, 2015). "The lack of correlation between STAT6 expression and tumor grade suggests that STAT6 is involved early in tumor development but is not dispensable later on as the tumor progresses." (PMID 21595984, 2011). "This suggests the possibility of synergistic benefits in response to global- rather than tumor specific- inhibition of STAT6 in vivo." (PMID 21595984, 2011). "A divergent pattern of phosphorylation of Zap70, LAT, Akt and STAT6 was noted in patients with or without an objective tumor response." (PMID 20856802, 2010). "However, it is of interest to note that STAT6 has been described as a signaling molecule downstream of Akt, suggesting to us that these changes after receiving tremelimumab may be reflective of a specific pathway modulation leading to more effective tumor targeting and killing." (PMID 20856802, 2010). "Our results demonstrate that STAT6 inhibition enhances iTreg differentiation and mitigates inflammation, though this immunomodulation alone is insufficient to prevent CAC development, highlighting the complexity of tumor-immune interactions in chronic inflammation." (PMID 41203944, 2025).
tumor (continued). "Additionally, phosphorylated STAT3 in cancer-associated fibroblasts (CAFs) drives angiogenesis and tumor growth, and phospho-STAT6 supports M2 macrophage polarization through JAK1 signaling, emphasizing the immunoregulatory impact of phosphorylation in the tumor microenvironment." (PMID 41359051, 2025). "Moreover, inhibiting STAT6 downregulates TGF-β levels and amplifies anti-tumor efficacy." (PMID 40370720, 2025). "Of note, STAT6 has been shown to be differentially expressed in tumor and non-tumor tissues." (PMID 41409600, 2025). "Immunohistochemistry of these tumor cells was negative for STAT-6, CD34, SMA, and S-100." (PMID 39432588, 2024). "Furthermore, 23-HBA effectively reduced the expression of p-STAT6 and CD206 in the tumor tissue." (PMID 38554148, 2024). "According to the medical data, tumour-infiltrating PD-L1+ T cells can act on PD-1+ macrophages and suppress M1 polarization by reducing NF-κB and signal transducer, as well as activator of transcription (STAT) 1 phosphorylation, but induce M2 polarization by increasing STAT6 phosphorylation." (PMID 39409156, 2024). "Basic leucine zipper ATF‐like transcription factor (BATF), involved in the synergistic induction of target gene expression, is further induced by co‐binding of STAT3 and STAT6, and high levels of BATF expressed from macrophages may contribute to tumor progression." (PMID 38098217, 2023). "In this study, we showed that RNA-targeting technologies (antisense oligonucleotides and CRISPR/CasRx) can be used to specifically suppress the expressions of NAB2–STAT6 fusion transcripts, but not wild type STAT6, and reduce cell proliferation and tumor growth." (PMID 37370737, 2023). "Notably, in the B16 melanoma tumour model, STAT6 has been demonstrated to induce M2 macrophage polarization and mediate the suppression of TRIM24 expression in M2 macrophages, contributing to the induction of an immunosuppressive tumour niche." (PMID 37491279, 2023). "CXCL12-activated CRC cells recruit macrophages to the invasive front of the tumor, and they induce their M2 polarization by transferring via exosomes a panel of miRNAs (including miR-25-3p, miR-130b-3p and miR-425-5p) that deplete PTEN transcripts and activate STAT6." (PMID 36831450, 2023). "This reduction in intracellular cholesterol enhances IL-4 receptor (IL-4R)/STAT6/PI3K signaling in vitro and in vivo, promoting the expression of the typical M2 marker arginase-1 while inhibiting NOS2 and proinflammatory IL-12 expression, thereby promoting tumor progression." (PMID 34876704, 2022). "Moreover, it was shown that after SOX21-AS1 silence, the apoptosis of tumor enhanced, while the expression of STAT6 exhibited no obvious change between different groups." (PMID 36335356, 2022). "Tumor cells of all detected cases were negative for STAT6 and S-100." (PMID 34350112, 2021). "However, the expression of STAT6 in tumor cells was mainly located in the cytoplasm rather than in the nucleus." (PMID 34906181, 2021). "By immunohistochemistry, the tumor cells stained positively for S-100 (focal +), CD34 (strong +++), and Ki-67 (20%), and negatively for smooth muscle actin, pan-cytokeratin (CK), neurofilament (NF), pan-cytokeratin-L, GFAP, CD31, STAT6, ERG, myogenin, and MyoD1." (PMID 32590748, 2020). "However, in contrast to human studies, STAT1, but not STAT3 or STAT6, was responsible for immunosuppressive activity of TAMs derived from colon CT-26 tumor-bearing BALB/c mice." (PMID 32486098, 2020). "To examine whether the Stat6-dependent effects on DNA damage were controlled by IL-4 receptor engagement in IEC, we generated Il-4rαΔIEC mice and examined their sensitivity to AOM injection as well as tumor incidence in the AOM/DSS model." (PMID 30353167, 2019). "Interestingly, exosomal miR-210 may derive from HCC cells, transfer into endothelial cells and promote tumor angiogenesis by inhibiting SMAD4 and signal transducer and activator of transcription 6 (STAT6)." (PMID 30897788, 2019).